RPL19 (ribosomal protein L19)
Description:
Component of the large ribosomal subunit. The ribosome is a large ribonucleoprotein complex responsible for the synthesis of proteins in the cell.
Synonyms: FLJ27452; MGC71997; DKFZp779D216; L19; eL19
Tractability: Small molecule: an approved drug acts on it; a structure with a bound ligand is known; a high-quality ligand is known. PROTAC: UniProt records ubiquitination sites on it; ubiquitination databases record sites on it; its protein half-life has been measured; a small molecule that binds it is known. Other modalities: a drug acting on it is in phase 2 or 3 trials.
Target class: Other cytosolic protein
Gene: Protein-coding gene on chromosome 17 (39,200,283 to 39,204,840, forward strand). Ensembl gene ENSG00000108298.
Subcellular location: Cytoplasm
Subcellular location (Human Protein Atlas): Cytosol; Nucleoli
Pathways (Reactome):
Metabolism of proteins: Eukaryotic Translation Termination; Formation of a pool of free 40S subunits; GTP hydrolysis and joining of the 60S ribosomal subunit; L13a-mediated translational silencing of Ceruloplasmin expression; PELO:HBS1L and ABCE1 dissociate a ribosome on a non-stop mRNA; Peptide chain elongation; Ribosome Quality Control (RQC) complex extracts and degrades nascent peptide; SRP-dependent cotranslational protein targeting to membrane; ZNF598 and the Ribosome-associated Quality Trigger (RQT) complex dissociate a ribosome stalled on a no-go mRNA
Metabolism of RNA: Major pathway of rRNA processing in the nucleolus and cytosol; Nonsense Mediated Decay (NMD) enhanced by the Exon Junction Complex (EJC); Nonsense Mediated Decay (NMD) independent of the Exon Junction Complex (EJC)
Cellular responses to stimuli: Response of EIF2AK4 (GCN2) to amino acid deficiency
Developmental Biology: Regulation of expression of SLITs and ROBOs
Disease: Viral mRNA Translation
Metabolism: Selenocysteine synthesis
Gene Ontology:
Molecular function: protein binding; RNA binding; structural constituent of ribosome
Biological process: cytoplasmic translation; negative regulation of myoblast fusion; spermatogenesis; striated muscle contraction; translation
Cellular component: cytoplasm; cytosol; cytosolic large ribosomal subunit; cytosolic ribosome; focal adhesion; membrane; nucleolus; ribosome; synapse
Genetic constraint (gnomAD): Loss-of-function variants: 1 observed, 17.1 expected, observed/expected ratio (o/e) 0.0585, 90% interval 0.02 to 0.28. The upper end of that interval is the gene's LOEUF score, 0.28, which puts it in group 1 of 6, group 1 being the genes least tolerant of losing a copy. Missense variants: 98 observed, 206.57 expected, observed/expected ratio (o/e) 0.47, 90% interval 0.4 to 0.56. Synonymous variants: 67 observed, 69.86 expected, observed/expected ratio (o/e) 0.96, 90% interval 0.79 to 1.17.
Homologues: Orthologues: dog RPL19 (100% identical), guinea pig RPL19 (100% identical), macaque RPL19 (100% identical), mouse Rpl19 (100% identical), rabbit RPL19 (99% identical), tropical clawed frog rpl19 (97% identical), zebrafish rpl19 (94% identical), Drosophila melanogaster RpL19 (75% identical), Caenorhabditis elegans rpl-19 (65% identical), rat Rpl19l4 (59% identical).